PTK7 (protein tyrosine kinase 7 (inactive))
Diseases named in the same sentence as PTK7 in open-access papers (continued):
Sharing a sentence is not in itself a finding about the gene and the disease.
tumor (continued). "Such events may require a specific cell context, potentially explaining inconsistencies between cell lines or tumor types, when examining the impact of PTK7 modulation." (PMID 25962058, 2015). "Furthermore PTK7 expression was significantly different with respect to tumor size (ANOVA, p = 0.033) in BC and nodal involvement (ANOVA, p = 0.007) in LN." (PMID 24409301, 2014). "High expression of PTK7 mRNA was significantly associated with higher NPI group (χ2 = 38.023, d.f. = 2, p < 0.001), ER-negative tumours (χ2 = 203.406, d.f. = 1, p < 0.001), PgR-negative tumours (χ2 = 69.697, d.f. = 1, p < 0.001), and HER2-positive tumours (χ2 = 38.726, d.f. = 1, p < 0.001)." (PMID 39335176, 2024). "Evidence is accumulating that PTK7 may be a promising anti-tumour target." (PMID 39335176, 2024). "Notably, the mice treated with PTK7-GEMs showed no body weight loss, further verifying that PTK7-GEMs effectively inhibited tumor metastasis without any adverse effects." (PMID 36471380, 2022). "The PTK7-GEMs might inhibit tumor growth and progression via multiple mechanisms." (PMID 36471380, 2022). "Therefore, the synthesized PTK7-GEMs could maintain good stability, which ensured the ideal blood concentration of PTK7-GEMs, and increased the chance of interaction between tumor tissue and aptamer-targeted drugs." (PMID 36471380, 2022). "Moreover, PTK7-GEMs, a single aptamer carrying three drug molecules, showed a higher delivery efficiency, also PTK7-GEMs could accurately deliver anticancer drugs and exert its strongly cytotoxicity toward target tumor cells." (PMID 36471380, 2022). "The malignant effect of the tumors resulted in weight loss in the GEM group being about 20%; however, in the PTK7-GEMs group only lost about 10% of their weight, with about 75% relative tumor growth inhibition, which was better than the GEM treatment group (55% tumor volume reduction)." (PMID 36471380, 2022). "Notably, PTK7-CAR2 T cells had a trend of producing a higher level of cytokines especially responding to stimulation by tumor cell lines expressing lower level of PTK7 (H1299 and BxPC3 cells), consistent with the higher level of CAR expression per cell in this construct." (PMID 34475869, 2021). "Moreover, PTK7 regulates tumor metastasis and collagen fibril organization via EGFR-Akt pathway." (PMID 34367983, 2021). "However, caution should be used with this strategy when considering the evidence showing PTK7 can biphasically regulate tumorigenesis, as the inhibition of PTK7 activity or removal of PTK7-positive cells may induce tumor progression." (PMID 29867084, 2018). "Moreover, MMP-9 expression positively correlated with PTK7 expression in ESCC tumor tissue." (PMID 27689325, 2016). "Thus, in our model, the impaired tumor growth in vivo in PTK7-depleted cells could rather result from an increase in apoptosis." (PMID 25962058, 2015). "Systematic PTK7 expression assessment in CDX and PDX models is essential to clarify the impact of tumor heterogeneity on efficacy." (PMID 40987771, 2025). "Instead, an unbiased analysis of multiple parameters through a machine learning approach identified a signature characterizing tumor response, based on the percentage of neutrophils, PD1+/TLs, and PTK7+/cDC2s." (PMID 40124507, 2025). "PF-06647020, a PTK7-targeted ADC made of a humanized antibody against PTK7 conjugated with the auristatin microtubule inhibitor Aur0101, also induced tumor regression in a subset of patient-derived xenograft models, without significant signs of toxicity." (PMID 39065798, 2024). "For example, PTK7 was identified as a ligand for Macrophage Galactose-type Lectin (MGL) on the surface of CRC cells, implicating PTK7 in CRC immune evasion and tumor growth." (PMID 39474113, 2024). "BCG033, an anti-PTK7 x TROP2 bispecific ADC, has shown potent anti-tumor activity in several PTK7/TROP2 co-expressing cell line-derived xenografts." (PMID 39474113, 2024).
tumor (continued). "In mouse xenograft tumor models, FOXP4 knockdown diminished tumor growth, yet reintroducing PTK7 partially reversed this effect." (PMID 38740744, 2024). "Consistent with the data from cultured cells, immunoblotting assays demonstrated the regulatory effect of miR‐503 on PTK7, FAK, and paxillin in mouse tumor tissues." (PMID 37212485, 2023). "Analysis of the 1097 tumor tissues and 113 normal tissues of BC in the TCGA database showed that the median level of PTK7 mRNA, Log2 (FPKM-UQ + 1), in tumor tissues (18.37) was significantly higher than that in normal tissues (17.64; p = 3.67 × 10−11)." (PMID 37569547, 2023). "In TNBC, the median level of PTK7 mRNA, Log2 (FPKM-UQ + 1), in 430 tumor tissues (18.80) was significantly higher than the median level in 90 normal tissues (17.50; p = 2.24 × 10−17)." (PMID 37569547, 2023). "Various studies have shown that PTK7 and FGFR1 are significantly upregulated in ESCC tumor tissues and cell lines." (PMID 35216506, 2022). "We previously found that knockdown of PTK7 reduces the oncogenic phenotypes of ESCC cells and inhibits tumor growth in xenograft mice with KYSE-30 cells." (PMID 36293051, 2022). "When tumor formation was observed after subcutaneous injection of KYSE-30 cells into the back, PTK7 mAbs (10 mg/kg) were injected intraperitoneally twice a week for three weeks." (PMID 36293051, 2022). "The tumor weight increased to 190.5 ± 17.2% in PTK7-overexpressing tumors with PTK7-FLAG, compared to the tumor weight (0.72 ± 0.11 g) of the mock control tumors." (PMID 35216506, 2022). "Therefore, it is expected that PTK7 mAb-43 may have better anti-tumor activity than PTK7 mAb-32." (PMID 36293051, 2022). "PTK7 overexpressed or knockdown TNBC cell lines (MDA-MB-468 and MDA-MB-436) were used to analyze the potential roles of PTK7 in TNBC metastasis and tumor progression." (PMID 34367983, 2021). "We found increased expression of FZD6, FZD7, RYK, and PTK7 in tumors, as well as a highly significant increase in FZD7 in tumor-adjacent cells." (PMID 31261741, 2019). "Thus, PTK7 prognostic impact could be dependent on tumor types and/or administered treatments." (PMID 25962058, 2015). "In PTK7 knockdown HCT15 cells, tumor volume was reduced by almost 50% (p = 0, 0125, two-way ANOVA) as compared to control cells." (PMID 25962058, 2015). "Tumor growth and metastatic phenotype were investigated in vivo using a xenograft mouse model of CRC cells with modulated expression of PTK7 levels." (PMID 25962058, 2015). "Thus, the function of PTK7 and Ror2 may depend on tumor context and ultimately on receptor context." (PMID 26680417, 2015). "To examine the tumorigenic activity of PTK7 in vivo, we subcutaneously transplanted bioluminescent HCT15 cells (shCTRL or shPTK7) in NSG mice and monitored both tumor growth and metastatic dissemination." (PMID 25962058, 2015). "Using data from TCGA, we analyzed PTK7 mRNA expression in both tumor and adjacent normal tissues, as well as in non-TNBC and TNBC." (PMID 39936972, 2025). "To investigate whether PTK7 mediates the tumor-promoting function of FOXP4 in OV, we generated FOXP4 knockout cells with stable expression of exogenous PTK7." (PMID 38740744, 2024). "Some of these TATs were essential for the survival of tumour cells like CD71, PSMA and PTK7." (PMID 37740463, 2023). "Similarly, niche indications for ADCs in clinical development included targets for CD71, PSMA, PTK7 or CD74, in tumours like breast, lung, stomach or colon." (PMID 37740463, 2023). "PTK7, SERPINH1, and FAP could discriminate PanIN versus tumor‐related stroma by contrast to αSMA and LRRC15." (PMID 36587397, 2023). "In addition, the maximum inhibition rate of PTK7-GEMs and GEM was about 85% on 5637 tumor cell line, while that of PTK7-GEMs toward normal bladder uroepithelial cells was lower than 45%; similar result was observed for the cell cycle and the apoptosis rate." (PMID 36471380, 2022).
tumor (continued). "IHC revealed markedly increased PTK7 expression in OSCC tumor tissue compared with that in the adjacent normal tissue, and strong staining was predominantly observed in the basal layer and invasive front of tumor tissue." (PMID 35257502, 2022). "Xenografted mice bearing PTK7-overexpressing KYSE-30 cells showed accelerated tumor growth compared to mock-control mice, while mice harboring PTK7-knockdown KYSE-30 cells exhibited a delay in tumor growth compared to control mice." (PMID 35216506, 2022). "As not all human tissues with PTK7 expression are represented, these studies are limited but can serve as an initial screen for off-tumor activity." (PMID 34475869, 2021). "Since on-target off-tumor toxicity is a key limiting factor when developing novel CAR T therapies, we roughly address this concern using a panel of primary human normal cell lines with low-level expression of PTK7." (PMID 34475869, 2021). "Furthermore, PTK7 regulates the activity of kinase insert domain receptor (KDR) and thereby participates in VEGF induced tumor angiogenesis." (PMID 34367983, 2021). "Previous studies identified PTK7 as a survival gene in ADC and demonstrated that inhibition of PTK7 by siRNA or monoclonal antibody could effectively impair tumor growth in vivo and in vitro." (PMID 29300342, 2018). "As PTK7 mRNA levels are already high in tumor tissues of ESCC patients, we were not able to detect a change in risk with lower levels of expression." (PMID 29867084, 2018). "In order to better understand the role of PTK7 in colorectal tumorigenesis, we examined its protein expression by immunohistochemistry on a TMA containing tumor tissues from 192 primary CRCs (the clinical characteristics of which are shown in S1 Table) and matched normal mucosa." (PMID 25962058, 2015). "Furthermore, tumor tissues from TNBC exhibited significantly higher PTK7 mRNA expression than non-TNBC tumor tissues." (PMID 39936972, 2025). "In TNBC patients, the PTK7 mRNA level in tumor tissues was much higher than that in normal tissues." (PMID 37569547, 2023). "SELEX has tested a number of aptamers targeting tumor cells, for example, A10 aptamer (against prostate-specific membrane antigen; PSMA), AS1411 aptamer (against nucleolin), EpCAM aptamer (against epithelial cell adhesion molecule), and Sgc8 aptamer (against protein tyrosine kinase 7; PTK7)." (PMID 37149607, 2023). "Had there been no inflammation or necrosis of the xenograft tumor, the tumor could have grown for another week, and the difference in tumor growth between the control group and the PTK7 mAb-treated group would have been more significant." (PMID 36293051, 2022). "Due to the mechanism of action of PTK7, counteracting PTK7 functions through PTK7 knockdown or treatment with PTK7 neutralizing antibody can significantly reduce tumorigenicity, though not completely regress the tumor cells." (PMID 36293051, 2022). "One proposed explanation for this is the role of PTK-7 is still not well-understood and may differ in each tumor type, compounding the difficulty of interpreting data." (PMID 31820857, 2020). "Second, we could not address whether PTK-7 expression in tumor tissue was higher than in normal mucosa as it was shown in most previous studies." (PMID 31820857, 2020). "Thus, aptamer sgc8c could not only help TDNs entry into the cell but also specifically target on PTK7‐positive cells (CCRF‐CEM), indicative of its potential application for the drug delivery of PTK7‐positive tumours." (PMID 30311693, 2019). "More recently, an aptamer (sgc8) selective for the protein tyrosine kinase 7 (PTK7) was 18F-radiolabeled and the resulting bioconjugate was used for the detection and the quantification by PET imaging of the expression of PTK7 both in vitro and in different tumor mouse models." (PMID 29144411, 2017).
tumor (continued). "Reasons for such different results are not clear, but in our xenograft experiments with HCT15 cells, tumor growth was significantly decreased in PTK7-depleted cells, whereas the Ki67 status did not shown any significant difference, consistently with in vitro results." (PMID 25962058, 2015). "To evaluate whether this pro-tumorigenic impact is due to difference in cell proliferation, we examined the Ki67 status in tumor xenografts, with and without PTK7 knockdown." (PMID 25962058, 2015). "However, these promising avenues merit further exploration, keeping in mind that the expression of PTK7 is not limited to tumor cells and that a better understanding of its role in non-tumoral cell populations is needed to anticipate possible adverse effects during the treatment." (PMID 38773263, 2024). "As PTK7 overexpression protects non-NC cells from NC invasion, it is tempting to speculate that PTK7 overexpression could also block invasion of PTK7 expressing tumor cells, although in a context-dependent manner." (PMID 34502237, 2021). "It was previously reported that xenograft tumor growth was significantly reduced in mice when TNBC cells with PTK7 knockdown were used, compared with mice xenografted with TNBC cells without PTK7 knockdown." (PMID 39936972, 2025). "To assess the potential value of PTK7 in the progression of BC, including TNBC, we analyzed the expression of PTK7 mRNA expression using The Cancer Genome Atlas (TCGA) database for tumor and adjacent non-tumor tissue samples of BC patients." (PMID 37569547, 2023). "In the short-term assays, PTK7-CAR T cells exhibited a robust dose-dependent cytotoxicity against PTK7-expressing PTK7-CHO cells and tumor cells but not parental CHO cells." (PMID 34475869, 2021). "Our choices of tumor models for these experiments, PSMA-expressing 22Rv1 cells or PC3-PSMA cells, express high levels of hTfR and PSMA (>10-fold staining as assessed by aptamer staining using flow cytometry), but low or no levels of EGFR and PTK7." (PMID 34725326, 2021).
infection (6 papers, 2014 to 2025). The state of being infected such as from the introduction of a foreign agent such as serum, vaccine, antigenic substance or organism. "Absolute quantification revealed a decrease in the expression of Ptk7 gene following an in utero CV-B4 infection." (PMID 32300341, 2020). "The evaluation of Ptk7 transcripts in the thymus, for its part, showed a decrease in expression, especially following an infection at day 10 of gestation, which supports the hypothesis of T cell accumulation in a mature stage in the thymus." (PMID 32300341, 2020). "A HeLa PTK7 K.O. cell pool showed decreased S. aureus invasion for short (10 min) but not for longer (30 min) infection times, suggesting involvement of PTK7 in the rapid Ca2+-/ASM-dependent internalization of S. aureus." (PMID 40162795, 2025). "This is in line with our current study since in utero infection of the thymus resulted in a nonsignificant increase of Ptk7 gene expression in fetal thymus, a gene mainly overexpressed by DN T cells." (PMID 32300341, 2020). "After transient infection of NIH3T3 cells with pLXSN/PTK7wt, pLXSN/PTK7DN, or pLXSN/v-src (positive control) focus formation and soft agar colony formation assays were performed in order to determine the transforming potential of PTK7." (PMID 24409301, 2014).
hematological malignancies (4 papers, 2021 to 2025). "PTK7 is a pseudokinase over-expressed in several solid tumors and hematological malignancies and linked to metastasis, poor prognosis, and resistance." (PMID 40124507, 2025). "One of the most recent developments was the design of CAR-specific binding aptamers (CAR-ap) that successfully combine for the first time the specificity of aptamers with the potency of immune effectors to selectively target PTK7 in the context of hematological malignancies." (PMID 38773263, 2024).
digestive system cancer (1 paper, 2024). A primary or metastatic malignant neoplasm involving any part of the digestive system. "In conclusion, the upregulation and carcinogenic role of PTK7 in digestive system cancers have been confirmed, and the molecular mechanisms behind this have been initially elucidated." (PMID 39474113, 2024). "How to target PTK7 in digestive system cancers is destined to become the focus of future research." (PMID 39474113, 2024).
PTK7 also shares sentences with these, for which no sentence is quoted: panic attacks (24 papers); depression (4); Burkitt lymphoma (2); familial colorectal cancer (2); gastric tumor (2); lymphoma (2); malnutrition (2); anencephaly (1); Anophthalmia (1); anxiety disorder (1); asthenia (1); benign prostatic hyperplasia (1); brain tumors (1); colorectal adenoma (1); cystic kidneys (1); diastematomyelia (1); endometrial cancer (1); enteropathies (1); epilepsy (1); gynecologic tumor (1); Hydrocephalus (1); Insulin resistance (1); invasive breast carcinoma (1); irritable bowel syndrome (1); lymphocytic leukemia (1); mesothelioma (1); metastasis (1); metastatic melanoma (1); Micrognathia (1); mood disorder (1).
A further 8 diseases each share a sentence with PTK7 in 1 paper.